IL4 (interleukin 4)
Diseases named in the same sentence as IL4 in open-access papers (continued):
Sharing a sentence is not in itself a finding about the gene and the disease.
tumor (continued). "Moreover, mast cells inhibit tumor cell growth, apoptosis, diffusion, and inflammation by releasing cytokines, including IL-1, IL-4, IL-6, TNF-α, and chondroitin sulphate." (PMID 36430483, 2022). "Habitually, DCs for tumor vaccines are generated from autologous monocytes (moDCs) in the presence of recombinant granulocyte-macrophage colony-stimulating factor (GM-CSF) and interleukin-4 (IL-4)." (PMID 35453618, 2022). "After being activated, CAR-T cells expressing these two receptors may be able to reverse the inhibitory signal transmitted by tumor cells as well as the inhibitory effect of IL-4 simultaneously." (PMID 35392217, 2022). "Based on the literature, not just the tumor cells but the tumor-associated and normal stroma cells can also modify the differentiation of moDCs in the presence of IL-4 and GM-CSF, resulting in upregulated expression of DC-SIGN." (PMID 36194602, 2022). "Interestingly, pro-inflammatory cytokines induce tumor granule neuron precursors differentiating into astrocytes, and then astrocyte-mediated IL-4 stimulates GAMs to produce insulin-like growth factor 1, thereby further promoting tumor progression." (PMID 35572545, 2022). "TAMs may be activated classically (known as the M1 type) by IFN-γ and TNF to suppress tumor progression, or alternatively (known as the M2 type) by IL-4 and IL-10 to promote tumor immune evasion in different conditions." (PMID 36230570, 2022). "The a-GalCer-loaded whole tumor vaccine primes iNKT in the lung-draining lymph nodes with the release of cytokines, including IL-4, IL-13, and IFN-γ, into the serum and is effective against established intracranial tumors but requires depletion of regulatory T cells (Treg)." (PMID 35163235, 2022). "IL-15, a type I cytokine together with IL-2, IL-4, IL-7, IL-9, and IL-21, promotes survival of T, B, and NK cells by binding to IL-15α, encoded by IL15RA, negatively regulating both carcinogenesis and tumor growth." (PMID 36432658, 2022). "Importantly, U87 cells treated with g82/165 + HDR polarized tumor-associated macrophages (TAM) toward an M1 phenotype, as indicated by an increase in TNF-α and a decrease in IL-4 secretions." (PMID 35165339, 2022). "Moreover, Th2 cells were thought to promote tumor progression by secreting cytokines such as IL-4 and IL-13." (PMID 36139554, 2022). "In addition, an enhancement of anti-tumor immunity and delays in tumor progression have been observed in vivo following the administration of neutralizing antibodies against IL-4." (PMID 36552602, 2022). "In addition, the ratio IFN-γ/IL-4 decreased in the tumour microenvironment of the EE group compared to the SE group, resulting in a more anti-inflammatory cytokine environment." (PMID 35008220, 2021). "Moreover, the basophil count was correlated with IL-4 expression in tumour-draining lymph nodes, supporting the role of basophil as the source of IL-4." (PMID 33923108, 2021). "In addition, it also induced the release of crucial cytokines (IL-2, IL-4, IL-12, and IL-15) needed for the activation of T cell and resultant anti-tumor immune responses." (PMID 34439380, 2021). "Using this strategy, IL-4/21 ICR (where the ectodomain of the IL-4R is fused to the endodomain of the IL-21R) CAR T cells were significantly more effective at eradicating IL-4+ tumours in vivo." (PMID 33401460, 2021). "However, whereas IL4 expression was not significantly altered in MyLa cells after co-culture with normal fibroblasts, co-culture with MF tumor-derived fibroblasts significantly increased IL4 expression in MyLa cells (p < 0.02)." (PMID 33941102, 2021). "Moreover, recruitment of basophils in tumor-draining lymph nodes of pancreatic ductal adenocarcinoma patients has been shown to be activated by T-cell-derived IL-3 to produce IL-4, inducing a tumor-promoting Th2 inflammation." (PMID 33418996, 2021). "Rapamycin reduced the secretion of IL-4 in tumor cells as well as YM1 in macrophages." (PMID 33959512, 2021).
tumor (continued). "However, the contribution of the interaction between the cells to tumor radioresistance was indirectly confirmed through recombinant proteins, such as IL-4 and YM1." (PMID 33959512, 2021). "For example, ILC2s’ rapid secretion of inflammatory cytokines IL-13 and IL-4 in human cells have been reported to promote tumor growth by recruitment of monocytic myeloid-derived suppressor cells, immune cells important for the inhibition of anti-tumor immunity." (PMID 34531874, 2021). "Among these significant genes of IL-4 signaling are CFLAR, ALOX5, PMAIP1, EGR1, NCF2, SLC39A8, and PEG10 which have been reported to be associated with tumor progression or chemotherapy-drug resistance through effecting proliferation and apoptosis in previous studies." (PMID 33506057, 2021). "Several cytokines have been reported to support tumor growth in MF such as IL-13, IL-15 and IL-4." (PMID 33941102, 2021). "Anti-IL-4 antibodies inhibited the tumor growth in human CC cell line Caco." (PMID 33450900, 2021). "Interestingly, the percentage of basophils and IL-4 expression level were higher in tumour-draining lymph nodes than non-tumour draining lymph nodes." (PMID 33923108, 2021). "sh‐c‐Myb or PD‐L1 alone into FLO‐1 cells increased Fas, IFN‐γ, and IL‐2 expression, but decreased FasL, IL‐4, and IL‐10 expression in the tumor tissues, and cotransfection of sh‐c‐Myb and PD‐L1 showed more significant trends compared with transfection of sh‐c‐Myb or PD‐L1 alone." (PMID 34586738, 2021). "We observed that IL-4 promotes a positive feedback loop by i) promoting NLRP3 nuclear localization, ii) boosting TOX expression and TOX+ cell proliferation, which upregulates IL-4, and iii) favoring a dominance of Th2 responses in advanced stages of the disease (tumor)." (PMID 34220814, 2021). "IL-4 has been observed to have a significant effect on tumour progression." (PMID 33808304, 2021). "With IL10 and IL4 secreted by tumor cells and macrophages, respectively, induced M2 polarization." (PMID 34447383, 2021). "While Th2 and Th17 cells may promote tumor growth through expression of immunosuppressive cytokines including IL-4, IL-5, IL-13, and IL-17A, although the contribution of these cells to the tumor immune landscape is not completely clear." (PMID 34202979, 2021). "Importantly, these cells were able to respond to tumor rechallenge at a distal site by proliferating and eliminating tumor cells in an IL-4-dependent manner." (PMID 34177932, 2021). "Taking into account tumor organization, we hypothesize that increased levels of IL-4 and IL-5 in earlier CRC stages (I-III) could be a result of production by Th2 cells rather than ILC2 cells." (PMID 35008550, 2021). "Moreover, eosinophils can also have a direct anti-tumor effect on the cancer cells by the release of IL-4 in the tumor microenvironment." (PMID 34283042, 2021). "Th2 (T helper type 2) cells could block T cell-induced tumor rejection by producing Th2 cytokines including IL-4 and IL-13, which can induce the formation of immunosuppressive type 2-polarized macrophages." (PMID 33450900, 2021). "Indeed, IL-4 produced by memory anti-OVA Th2 cells directly stimulated natural killer (NK) cells cytotoxic activity against tumor." (PMID 34262562, 2021). "In addition, IL4 expression in ILC2s obtained from tumor tissues was higher than NSCLC PBMCs, while there was no distinction in IL13 expression between these two groups." (PMID 34194433, 2021). "Therefore, IL-4 can be used as a target for tumor immunotherapy due to its role in the tumor microenvironment." (PMID 34386015, 2021). "Elevated expression of NLRP3 in cells with high expression of IL-4 was observed in the tumor stage." (PMID 34220814, 2021). "Moreover, Th9 cells differentiated in presence of TGFβ and IL-4 harbor higher anti-tumor activity when IL-1β is present." (PMID 33498483, 2021). "Some authors proposed a mechanism of immune escape for tumor-initiating cells related to IL-4." (PMID 35008550, 2021).
tumor (continued). "Moreover, it has been demonstrated that downregulation of IL-4/IL-13 receptors showed suppression of tumor activity in other cancers." (PMID 33804263, 2021). "This implied that certain factors in the tumor microenvironment might further boost the upregulation of IL-4 and IL-13 in tumor tissues." (PMID 34194433, 2021). "Notably, tumor cells can promote M2 polarization by expressing cytokines and growth factors including colony-stimulating factor 1 (CSF-1) and IL-4." (PMID 33916915, 2021). "Within the tumor microenvironment, GAM are forced to transform to M2 phenotypes by GBM cells that secrete factors such as IL-10, IL-4, IL-6, macrophage colony-stimulating factor, macrophage inhibitory factor, TGFβ, and prostaglandin E2, which subsequently supports tumor growth and invasion." (PMID 34267749, 2021). "However, when they used BM cells, a heterogeneous population that includes myeloid progenitors, in a GM-CSF, IL-4, and 20% tumor supernatant culture, those progeny were functionally impaired in their ability to activate T cells." (PMID 33919157, 2021). "In contrast, enriched biological processes of inflamed TME-specific mRNA tended to be shared across tumor types, for example, signaling by interleukins (interleukin-4/13/10) and chemokines and PD-1 signaling, suggesting a recruiting and inhibitory tumor microenvironment for such inflamed tumors." (PMID 34059678, 2021). "Th2 in a tumor microenvironment is a great source of IL-4, IL-5 and IL-13." (PMID 34071442, 2021). "Under the influence of tumor-derived cytokine and growth factors [e.g., VEGF, granulocyte macrophage colony stimulating factor (GM-CSF), macrophage colony-stimulating factor (M-CSF), TGF-β, IL-4, IL-6, and IL-10], MDSCs acquire inhibitory activity against various anti-tumor immune cells." (PMID 34988072, 2021). "However, the alternatively activated microglia/macrophages promote tumor survival by producing anti-inflammatory cytokines such as IL-4, transforming growth factor-beta (TGF-β), and IL-10, defined as M2 markers." (PMID 34267749, 2021). "IFN-γ secreted by Th1 cells can cause the activation of cytotoxic CD8+ T cells, dendritic cells (DCs), and macrophages, producing effective anti-tumor effects; Th2 cells mainly secrete IL-4, which can lead to the activation of tumor-promoting macrophages to promote tumor growth." (PMID 34553029, 2021). "Furthermore, injection of IL-4 enhanced tumor clearance and correlated with increased infiltration of eosinophils, macrophages, neutrophils and in part lymphocytes." (PMID 34135885, 2021). "Bexarotene, by inducing malignant T-cell apoptosis and suppression of IL-4 production, may stimulate an anti-tumor response in responder patients." (PMID 34685762, 2021). "Here, we show in a myeloid-specific knockout (KO) model in an unbiased manner that loss of Acly diminishes IL-4-responses and that the altered phenotype of AclyM-KO TAMs does not affect tumor growth." (PMID 34205266, 2021). "Tumor-associated macrophages (TAMs) inhepatocellularcarcinoma (HCC) play a prominent role in tumormicroenvironment by presenting M1(induced by IFN γ along with LPS) and M2(induced by IL-4 and IL13) polarization." (PMID 33859517, 2021). "On the other hand, hypoxia induced release of chemoattractants (such as HIF-1α and HIF-2α) and tumor derived cytokines (such as IL-10, IL-4, and TGF-β) are able to hijack tumor-associated macrophages (TAMs) and tumor-associated dendritic cells (TADCs) functions, resulting in tumor metastasis." (PMID 33761933, 2021). "Th2 cytokines such as IL-4, IL-10, IL-5, IL-9, and IL-6 can down-regulate tumor-specific immunity." (PMID 34222249, 2021).
tumor (continued). "Physiologically, IL-4 acts directly on tumour cells as a tumour-promoting cytokine." (PMID 33808304, 2021). "Moreover, previous studies have shown that tumor-infiltrating T-cell follicular helper produced IL4 to suppress antitumor immunity by inducing myeloid cells to differentiate into M2 macrophages." (PMID 32793475, 2020). "Along this line, C26‐bearing mice were treated with IL4 after having excluded, by in vitro experiments, the possibility that IL4 could exert a direct effect on tumour cells." (PMID 32103619, 2020). "This approach could enhance antitumor activity of these gene-modified CAR T cells in an IL-4-rich tumor microenvironment." (PMID 32391013, 2020). "In this regard, further experiments are required to clarify if systemic IL4 administration might exert different actions at the tumour and muscle levels, respectively." (PMID 32103619, 2020). "Also, IL-4 produced by tumor cells not only promotes M2-type polarization of macrophage, but also promotes tumor growth and invasion by enhancing the cathepsin protease activity in TAMs." (PMID 33224886, 2020). "Additionally, STAT6 is an important target protein of IL-4 that likely regulates the microenvironment of tumor cell growth, inhibits tumor invasion, and reduces tumor proliferation and differentiation." (PMID 33013320, 2020). "The relationship between IL-4 levels in the tumor microenvironment and an unproductive tumor vasculature remains unclear." (PMID 33255425, 2020). "Crosstalk between tumor-derived EVs and macrophages can polarize them toward a more M2-like, pro-tumor TAM, which is associated with higher levels of the immunosuppressive cytokines IL10, IL4, and TGFβ." (PMID 32547552, 2020). "IL-4 is a typical pleiotropic Th2 cytokine, which was found to directly induce tumor cell proliferation and to mediate resistance to apoptosis, supporting tumor growth." (PMID 33312693, 2020). "In multivariable Cox regression analyses, in addition to IL-4 (hazard ratio (HR) 2.8 (95% confidence interval (CI): 0.78–9.9); p = 0.116), the age-adjusted IL-8 level (HR 3.9 (95% CI: 1.05–14.5); p = 0.042) predicted tumor recurrence." (PMID 33255425, 2020). "The classic Th2 cytokine is interleukin-4 which, in addition to interleukin-13, may induce tumor clearance." (PMID 33569063, 2020). "Similarly, NK cells’ potential to eliminate tumor cells and functional interaction with DCs can be reduced by IL-4 produced and released into the TME." (PMID 32391048, 2020). "Thus, IL-4 neutralization represents an interesting tool for favoring IL-12-producing cDC1-driven anti-tumor effector modules facilitating the expansion of functionally active tumor infiltrating T cells, thereby limiting tumor progression." (PMID 32674488, 2020). "Moreover, reduced Cdc42 expression was observed in tumor-infiltrating iNKT cells, which impaired IL4 polarization and disturbed iNKT cell-DC crosstalk in tumors." (PMID 31160756, 2020). "In addition, tumours taken from female mice had significantly more IL-4 + CD4 + T cells, also correlated with increased survival." (PMID 32451467, 2020). "Similarly, in many types of cancer, T cells interact with tumor-associated microglia/macrophages (TAMs) through the secretion of factors, like IL-4 and IL-1364 and alter tumor growth or invasion." (PMID 32358581, 2020). "Moreover, activation of M2 macrophages due to factors like IL-13, IL-10, IL-4, and glucocorticoid, promote tumor growth by secreting high levels of IL-10 and low levels of IL-12." (PMID 33133086, 2020). "Moreover, concanavalin A-stimulated Vδ1 T cells cultured with IL-4 retain their cytotoxic properties against tumor cells." (PMID 33042132, 2020). "Because IL4-MΦ enhanced MT orientation in tumor cells, we hypothesized that co-cultured IL4-MΦ would also influence tumor cell shape." (PMID 32665556, 2020).
tumor (continued). "IL-4, in turn, is a cytokine expressed and produced by activated T-helper type 2 (Th2) lymphocytes and basophils, which has regulatory actions on allergic responses, as well as anti-tumor and anti-inflammatory effects." (PMID 32793635, 2020). "Several lines of evidence support a pro-tumor effect of IL-4 and IL-13 in vivo." (PMID 33371444, 2020). "Finally, a survival experiment demonstrated that IL4‐treated C26‐bearing mice were able to survive longer than untreated tumour hosts (31 days for C26 + IL4 vs. 13 days for C26)." (PMID 32103619, 2020). "Based on these results, preoperative serum interleukin-4 levels can play a role in predicting T cell responses specific for tumor-associated antigens and recurrence-free survival regardless of tumor stage." (PMID 33255425, 2020). "Its application to the analysis of the joint behavior of IFN-γ, IL-2, IL-10 and IL-4 showed that the differences observed in the growth of M-406 tumor could be explained by the first two main components." (PMID 33312693, 2020). "Tumor-associated cells residing at the tumor site, including immature dendritic cells (DCs), Tregs, tumor-associated macrophages, and myeloid-derived suppressor cells, produce various molecules such as TGF-β, IL-4, IL-10, prostaglandin E2, and idoleamine 2,3-dioxygenase." (PMID 32391048, 2020). "The level of IL-4 protein upregulation in tumor tissue was comparable between anatomical sites, whether expressed as mean difference (MD) or fold-change (tumor-to-adjacent ratio)." (PMID 32512917, 2020). "Furthermore, many tumor cells release cytokines, chemokines, and growth factors that recruit and induce FOXP3+ Tregs, and induce MDSCs and macrophages to release Th2 cytokines such as Tgf-β, IL-4, IL-10, and IL-13 which suppress anti-tumor immunity." (PMID 32508830, 2020). "The overexpression of CXCR3 might decrease proportion of Th2 cells and IL-4 level, reducing M2 macrophage infiltration and increased the dendritic cell and tumor-infiltrating lymphocyte." (PMID 33585188, 2020). "Moreover, detection of inflammatory cytokines showed that Kejinyan decoction downregulated TNF-α, IFN-γ, IL-6, as well as IL-4, IL-13 in tumor microenvironment." (PMID 32943999, 2020). "Other studies have demonstrated that pharmacologic inhibition of Axl decreases IL-4 expression in the tumor, which promotes tumor progression and metastasis through mediating proliferation and survival of lymphocytes, and macrophage polarization towards the M2-like phenotype." (PMID 32660000, 2020). "We found that IL-4 is significantly reduced in the BALF of STAT6−/− tumor-bearing mice." (PMID 31798581, 2019). "Indeed, IL-4 overexpression in combination with phthalic anhydride-induced allergy induction in mice enhances NK cell activity and reduces tumor burden." (PMID 31781102, 2019). "The results showed that both anti-inflammatory cytokines, such as IL-4 and IL-10, were up-regulated in tumours derived from animals that had previous exposure with the EDC, while the expression of the pro-inflammatory counterpart (TNF-α and IFN-γ) was diminished." (PMID 31731436, 2019). "Moreover, tumor cells can escape immune surveillance cells, promoting immune tolerance to the tumor by favoring the establishment of a Th2 immune response, expressing cytokines like IL-4, IL-10, and TGF-β." (PMID 31861795, 2019). "Similar to TGFβ, IL-10 and IL-4 have dynamic effects on tumor promotion and progression." (PMID 31174326, 2019). "Th2 cytokines, such as IL-4 and IL-13, can polarize macrophages into the M2 phenotype, and M2 macrophages function in anti-inflammatory processes, tissue repair and remodeling, parasite clearance, tumor-promoting processes and immunoregulatory processes." (PMID 31192126, 2019).